TSHZ3 (teashirt zinc finger homeobox 3)
Description:
Transcriptional regulator involved in developmental processes. Functions in association with APBB1, SET and HDAC factors as a transcriptional repressor, that inhibits the expression of CASP4. TSHZ3-mediated transcription repression involves the recruitment of histone deacetylases HDAC1 and HDAC2. Associates with chromatin in a region surrounding the CASP4 transcriptional start site(s). Regulates the development of neurons involved in both respiratory rhythm and airflow control. Promotes maintenance of nucleus ambiguus (nA) motoneurons, which govern upper airway function, and establishes a respiratory rhythm generator (RRG) activity compatible with survival at birth. Involved in the differentiation of the proximal uretic smooth muscle cells during developmental processes. Involved in the up-regulation of myocardin, that directs the expression of smooth muscle cells in the proximal ureter (By similarity). Involved in the modulation of glutamatergic synaptic transmission and long-term synaptic potentiation (By similarity).
Synonyms: KIAA1474; TSH3; ZNF537
Tractability: Antibody: its Gene Ontology location is reachable by antibodies, with high confidence. PROTAC: ubiquitination databases record sites on it.
Gene: Protein-coding gene on chromosome 19 (31,149,979 to 31,349,436, reverse strand). Ensembl gene ENSG00000121297.
Subcellular location: Nucleus; Cell projection, growth cone
Subcellular location (Human Protein Atlas): Nucleoplasm; Plasma membrane
Gene Ontology:
Molecular function: chromatin binding; protein binding; DNA binding; DNA-binding transcription factor activity, RNA polymerase II-specific
Biological process: negative regulation of DNA-templated transcription; long-term synaptic potentiation; positive regulation of synaptic transmission, glutamatergic; regulation of respiratory gaseous exchange by nervous system process; regulation of transcription by RNA polymerase II; regulation of gene expression
Cellular component: nucleoplasm; nucleus; chromatin; growth cone
Genetic constraint (gnomAD): Loss-of-function variants: 10 observed, 64.46 expected, observed/expected ratio (o/e) 0.16, 90% interval 0.095 to 0.26. The upper end of that interval is the gene's LOEUF score, 0.26, which puts it in group 1 of 6, group 1 being the genes least tolerant of losing a copy. Missense variants: 1,241 observed, 1,461 expected, observed/expected ratio (o/e) 0.85, 90% interval 0.81 to 0.89. Synonymous variants: 607 observed, 612.87 expected, observed/expected ratio (o/e) 0.99, 90% interval 0.93 to 1.06.
Homologues: Orthologues: chimpanzee TSHZ3 (99% identical), macaque TSHZ3 (99% identical), guinea pig TSHZ3 (96% identical), mouse Tshz3 (95% identical), dog TSHZ3 (94% identical), rat Tshz3 (94% identical), rabbit TSHZ3 (91% identical), pig TSHZ3 (89% identical), tropical clawed frog tshz3 (86% identical), zebrafish tshz3b (74% identical), Drosophila melanogaster tio (15% identical), Drosophila melanogaster tsh (14% identical). Paralogues in human: TSHZ1 (58% identical), TSHZ2 (46% identical).